FLT3 (fms related receptor tyrosine kinase 3)
Diseases named in the same sentence as FLT3 in open-access papers (continued):
Sharing a sentence is not in itself a finding about the gene and the disease.
acute myeloid leukemia (continued). "Gilteritinib, a small molecule, is an inhibitor of FMS-like tyrosine kinase 3 (FLT3) and is approved by FDA for treating acute myeloid leukemia (AML)." (PMID 34572902, 2021). "Classification of acute myeloid leukaemia patients’ NPM1 and FLT3-ITD genotypes (August 2020, Bloemfontein, Free State, South Africa)." (PMID 34230878, 2021). "FMS-like tyrosine kinase 3 (FLT3) mutations with internal tandem duplication (ITD) are associated with high leukemic burden and poor prognosis in patients with acute myeloid leukemia (AML)." (PMID 34834162, 2021). "For example, the three genes GRB2, FLT3, and PML, which were found in the acute myeloid leukemia (AML) signaling network, were considered key drug target genes." (PMID 34238960, 2021). "FLT3-mutant acute myeloid leukemia (AML) is an aggressive form of leukemia with poor prognosis." (PMID 33799721, 2021). "However, in acute myeloid leukemia (AML) patients with activating mutations in FMS‐like tyrosine kinase 3 (FLT3), USP10 deubiquitinates and stabilizes FLT3 by removing the proteolytic polyubiquitin chains and preventing FLT3 degradation, to aggravate tumor progress." (PMID 31721429, 2020). "In acute myeloid leukemia (AML), blasts express FLT3, and deregulation of its signaling pathway leads to exacerbated cellular proliferation, either by hyperstimulation or mutations, both of which contribute to AML onset." (PMID 32283751, 2020). "C/EBPα function is indeed frequently abrogated in acute myelogenous leukemias (AML) and oncogenes, such as AML1-ETO, BCR-ABL, or FLT3-ITD." (PMID 32560326, 2020). "Treatment of acute myeloid leukemia (AML) remains inefficient due to drug resistance and relapse, particularly in patients with FMS-like tyrosine kinase 3 (FLT3)-internal tandem duplication (ITD)." (PMID 31963113, 2020). "Mutations in the FMS-like tyrosine kinase 3 gene (FLT3), involved in regulating survival, proliferation, and differentiation of hematopoietic stem/progenitor cells, are common in acute myeloid leukemia (AML)." (PMID 32629802, 2020). "Treatment of FMS-like tyrosine kinase 3 (FLT3)-internal tandem duplication (ITD)-positive acute myeloid leukemia (AML) remains a challenge despite the development of novel FLT3-directed tyrosine kinase inhibitors (TKI); the relapse rate is still high even after allogeneic stem cell transplantation." (PMID 33212779, 2020). "However, in acute myeloid leukemia (AML) cells, ceramide synthesis is suppressed by Fms-like tyrosine kinase 3 (FLT3)-internal tandem duplication (ITD) signaling, which confers its resistance to cell death." (PMID 32274386, 2020). "In contrast, circMYBL2 exacerbates acute myeloid leukemia by strengthening the interaction between PTBP1 and FMS-like tyrosine kinase 3 (FLT3) mRNA and promoting translation." (PMID 33317550, 2020). "Sorafenib is a kinase inhibitor drug approved for the treatment of primary kidney cancer, advanced primary liver cancer, FLT3 internal tandem duplication (FLT3-ITD) positive acute myeloid leukemia (AML), and radioactive iodine resistant advanced thyroid carcinoma." (PMID 33163086, 2020). "Targets that have been studied in acute myeloid leukemia include CD33, CD135, FLT3, CXCR4, and vascular endothelial growth factor." (PMID 30621282, 2019). "FLT3 tyrosine kinase inhibitor, midostaurin (PKC412), is tested in phase 1 and 2 clinical study for acute myeloid leukemia in combination with HDM-201 (NCT03760445)." (PMID 31331108, 2019). "Compound 8t also showed excellent inhibitory activity against a variety of FLT3 mutants (IC50 < 5 nM), and potent anti-proliferative effect within the nanomolar range on acute myeloid leukemia (MV4-11, IC50: 1.22 nM)." (PMID 31731727, 2019). "Likewise, a new, STAT5 inhibitor suppressed the proliferation of human acute myeloid leukemia (AML) cell lines and primary FLT3-ITD+ AML patient cells." (PMID 31684144, 2019).
acute myeloid leukemia (continued). "We observed that acute lymphoblastic leukemia (ALL) and FLT3-ITD-positive acute myeloid leukemia (AML) patients with higher expression of P2RY14 mRNA displayed relatively poor survival compared to patients carrying lower expression of P2RY14 suggesting a role of P2RY14 in patient survival." (PMID 29951132, 2018). "Targeted therapies for the treatment of acute myeloid leukemia (AML), specifically the FLT3 inhibitors, have shown promising results." (PMID 29262547, 2017). "Quizartinib (AC220), a potent class III receptor tyrosine kinase inhibitor (TKI), was synthesized to selectively inhibit FMS-like tyrosine kinase-3 (FLT3), a target in the treatment of acute myeloid leukemia (AML)." (PMID 29212189, 2017). "Selective inhibition of FLT3, HDAC3 or HDAC6 have been proved useful for the treatment of acute myeloid leukemias, but the benefits of combinations of HDAC3, HDAC6 and FLT3 inhibitors were rarely reported." (PMID 29262547, 2017). "Oncogenic FLT3 kinase is a clinically validated target in acute myeloid leukemia (AML), and both multi-targeted and selective FLT3 inhibitors have been developed." (PMID 28881711, 2017). "Constitutively activating mutations of FLT3 map predominately to the juxtamembrane domain (internal tandem duplications; ITD) or the activation loop (AL) of the kinase domain and are detected in about 1/3 of de novo acute myeloid leukemia (AML) patients." (PMID 28077790, 2017). "Moreover, high levels of AXL are involved in crizotinib (ALK inhibitor) resistance in lung cancer patients and contribute to FLT3 inhibitor resistance in acute myeloid leukemia (AML)." (PMID 27590506, 2016). "The inhibition of FMS-like tyrosine kinase 3 (FLT3) activity using small-molecule inhibitors has emerged as a target-based alternative to traditional chemotherapy for the treatment of acute myeloid leukemia (AML)." (PMID 26118648, 2015). "FLT3 has been identified as a valid target for the treatment of acute myeloid leukemia (AML), and some FLT3 inhibitors have shown very good efficacy in treating AML in clinical trials." (PMID 26497577, 2015). "Few molecular markers have been used to predict treatment response and prognosis in cytogenetically normal acute myeloid leukemia (CN-AML), such as the nucleoplasmin (NPM1) gene and the fms-like tyrosine kinase 3 (FLT3) gene." (PMID 24667279, 2014). "We demonstrate applications in large-scale disease studies, by identifying PTDs in MLL, ITDs in FLT3, and reciprocal fusions between PML and RARA, in two deeply sequenced acute myeloid leukemia (AML) RNA-seq datasets." (PMID 23941359, 2013). "We further demonstrated how deregulation of Flt3 due to a misfolded conformation dependent loss (MCDL) of N-CoR contributed to the malignant growth and transformation of cells in acute myeloid leukemia of the FAB-M5 subtype (AML-M5)." (PMID 23940660, 2013). "FLT3-ITD and FLT3-TKD mutations are frequently found in acute myeloid leukemia (AML)." (PMID 23216927, 2012). "Prognostic markers, such as NPM1, Flt3-ITD, and cytogenetic abnormalities have made it possible to formulate aggressive treatment plans for unfavorable acute myeloid leukemia (AML)." (PMID 20416083, 2010). "FLT3 is also expressed on leukemia blasts in most cases of acute myeloid leukemia (AML)." (PMID 19330068, 2008). "Similarly, CD99 regulates FLT3-ITD localization, suggesting its potential in immunotherapy for acute myeloid leukemia." (PMID 40427525, 2025). "In acute myeloid leukemia, BCL2A1 may become a novel therapeutic target for treating FLT3-ITD/D835 mutant AML." (PMID 40707992, 2025). "There is no established standard treatment for acute myeloid leukemia (AML) patients with FLT3 wild-type relapsing after allogeneic hematopoietic stem cell transplantation (allo-HSCT)." (PMID 40830801, 2025).
acute myeloid leukemia (continued). "Our previous work also reported potent activity of CDDD11-8 against a limited number of other kinases, in particular the fms-like tyrosine kinase 3 (FLT3) protein, and its mutant form (FLT3-ITD), a known driver and therapeutic target in acute myeloid leukaemia." (PMID 38001268, 2024). "(A) Schematic representation of the FLT3-internal tandem duplication (ITD) prior knowledge network (PKN) manual curation, integration of data-driven edges, and manual integration of RTKs pathways involved in acute myeloid leukemia (AML)." (PMID 38564252, 2024). "In acute myeloid leukemia, a preclinical study found a promising and potent anti-leukemic strategy involving the co-administration of midostaurin (a TKI that inhibits the FLT3 pathway) and a novel FLT3-targeting ADC." (PMID 38178200, 2024). "In the setting of acute myeloid leukemia (AML), patient-drug treatment matching fails in a subset of patients harboring atypical internal tandem duplications (ITDs) in the tyrosine kinase domain of the FLT3 gene." (PMID 38564252, 2024). "Furthermore, suppression of tyrosine kinase FLT3-ITD, p22phox, and NOX4 activity in acute myeloid leukemia (AML) cells leads to reduced cell survivability and reductions in DNA damage and genomic instability according to the research." (PMID 37894287, 2023). "Similarly, the enhancer activity of h-FLT3 was supported by more robust H3K27ac ChIP-seq signals in MLL-r acute myeloid leukemia (AML) cells (MOLM13, MOLM14, and MV4;11 cells) as compared with non-MLL-r AML cells (IMSM2, HEL, K562, SET2, U937, and HL60 cells) and normal CD34+ cells 35–37." (PMID 38016946, 2023). "In acute myeloid leukemia (AML), one of the most common types of leukemia, silvestrol was shown to exhibit significant in vivo and in vitro activities through a novel mechanism resulting in inhibition of FLT3 (FMS-like tyrosine kinase receptor-3) and miR-155 (microRNA) expression." (PMID 34104125, 2022). "Our approach is effective even in tumors with large genetic heterogeneity such as acute myeloid leukemia, where we identified LEDs not recalled by previous pipelines, including FLT3-mutant genotypes sensitive to FLT3 inhibitors." (PMID 35805023, 2022). "The in-frame internal tandem duplication (ITD) of the FMS-like tyrosine kinase 3 (FLT3) gene is an important negative prognostic marker in acute myeloid leukemia (AML)." (PMID 36551616, 2022). "However, these variant types can be clinically important, for example, IKZF1 deletions in acute lymphoblastic leukaemia, FLT3 internal tandem duplications (ITDs) and MLL partial tandem duplications (PTDs) in acute myeloid leukaemia." (PMID 34686194, 2021). "The tumor-suppressive role of ceramide-induced mitophagy is also evident from the study in acute myeloid leukemia (AML), where FLT3-ITD (mutant Fms-like tyrosine kinase 3–internal tandem duplication) signaling downregulated the CerS1/C18-ceramide which confers its resistance to cell death." (PMID 35011599, 2021). "In addition, we ran MINTIE on RNA-seq samples from acute myeloid leukaemia (AML) and normal blood, where we confirmed its sensitivity in detecting FLT3-ITDs, KMT2A-PTDs and fusions on real data." (PMID 34686194, 2021). "We report successful targeted therapy against non-ITD, non-D835 driver FLT3 alterations in two patient case studies with acute myeloid leukemia." (PMID 32984009, 2020). "We present a case of a 32-year-old male on ruxolitinib with GVHD status postmatched unrelated donor stem cell transplant (MUD SCT) for acute myeloid leukemia (AML) with FLT3 mutation currently on ruxolitinib for 5 years who is not able to tolerate reduction in dosage due to flare-ups." (PMID 32318300, 2020).
acute myeloid leukemia (continued). "In vitro and murine studies demonstrated that constitutively active Flt3 mutants allow acute myeloid leukemia cells to grow in the absence of interleukin 3 (IL-3)." (PMID 33363015, 2020). "Molecular studies revealed a lack of mutations in CEBPA, FLT3 ITD, FLT3 TKD\T\, and NPM1, which are commonly seen in other types of acute myeloid leukemia." (PMID 32782874, 2020). "For binase, the selective cytotoxicity toward cancer cell lines expressing certain oncogenes, namely ras, kit, acute myelogenous leukemia 1 AML1) transcription factor and the eight-twenty one (ETO) corepressor, and FMS-like tyrosine kinase 3 (FLT3), has been previously demonstrated." (PMID 33375305, 2020). "Multi-kinase inhibitors targeting mainly FLT3 are generally accepted for acute myeloid leukemia (AML) treatment but are not clinically used on solid tumors due to low efficacy." (PMID 31554189, 2019). "In acute myeloid leukemia (AML), overexpression and constitutive activation of the FLT3 receptor tyrosine kinase induces a strong activation of STAT5, which can be inhibited by an FLT3 protein tyrosine kinase inhibitor." (PMID 30262727, 2018). "Acute myeloid leukemia (AML) is a highly heterogeneous disease and internal tandem duplication mutation in FMS-like tyrosine-kinase-3 (FLT3-ITD) has a negative impact on outcome." (PMID 28061447, 2017). "The phosphoSTAT5 — miR-21 — PDCD4 pathway was active in CML primary CD34+ cells, but also in acute myeloid leukemia (AML) models like MV4.11 and MOLM13, where the constitutively active tyrosine kinase FLT3-ITD plays a similar role to BCR-ABL1 in the K562 cell line." (PMID 29100302, 2017). "The receptor tyrosine kinase FLT3 belongs to the type III receptor tyrosine kinase family and is preferentially expressed in acute myeloid leukemia (AML) and acute lymphocytic leukemia (ALL) cells in addition to hematopoietic stem cells, brain, placenta and liver." (PMID 26895103, 2016). "In acute myeloid leukemia (AML), ROCK1 depletion by genetic knockout or ROCK inhibition with H-1152, Y27632, or fasudil reduced the survival of malignant cells bearing oncogenic form of KIT, FLT3, and BCR-ABL through suppressing MLC phosphorylation." (PMID 26725045, 2016). "Overall these findings demonstrate that the pathogenesis of MLL-ENL acute myeloid leukemias does not require Flt3 signaling." (PMID 23977266, 2013). "Both the World Health Organization and the European Leukemia Net classifications have included molecular markers such as NPM1, FLT3 and CEBPA as a prognostic factor for cytogenetically normal-acute myeloid leukemia (CN-AML) reinforcing their importance in cytogenetics." (PMID 23941109, 2013). "Previous studies have shown that constitutive activation of FLT-3 is involved in leukemogenesis, partially through phosphorylation/activation of the serine-threonine kinase AKT, which occurs in a substantial subset of acute myeloid leukemia (AML) cases." (PMID 21067588, 2010). "The development of FLT3-ITD inhibitors, such as AC220, represents a novel therapeutic strategy for acute myeloid leukemia (AML)." (PMID 40710514, 2025). "In addition, circMYBL2 (derived from the cell cycle checkpoint gene MYBL2) facilitates protein translation and exacerbates acute myeloid leukemia by enhancing the interaction between polypyrimidine tract-binding protein 1 (PTBP1) and FMS-like tyrosine kinase 3 (FLT3) mRNA." (PMID 39062737, 2024). "Specifically, multiomics analyses highlighted an increase in lipid anabolism when C/EBPα and Fms-like tyrosine kinase 3 (FLT3) were coordinately activated in in vivo experiments and in patients with FLT3-mutant acute myeloid leukemia (AML)." (PMID 38137407, 2023). "FLX925 selectively acts on FLT3 and CDK4/6, and its current indication is acute myeloid leukemia (AML)." (PMID 38138549, 2023).
acute myeloid leukemia (continued). "Next‐generation inhibitors, such as quizartinib or gilteritinib, are more specific and potent FLT3 inhibitors with more favourable toxicity profiles; however, to date, these drugs are approved only for acute myeloid leukaemia, and thus no data on their activity in solid tumours are available." (PMID 36670542, 2023). "Another work reported the use of a nanoparticle-complex based on different FLT3 inhibitors, namely Midostaurin, Sorafenib, Lestaurtinib, and Quizartinib, which were independently loaded onto gelatin-coated gold nanoparticles with promising results against THP1 acute myeloid leukemia cells." (PMID 37623644, 2023). "Information concerning the molecular role of TET2 mutation in cooperation with “driver” mutations has largely been garnered from genetic mouse models of acute myeloid leukemia (AML), including TET2–/–Flt3-ITD and TET2–/–AML-ETO mice." (PMID 35393954, 2022). "Internal tandem duplication (ITD) of FMS-like tyrosine kinase 3 (FLT3) confers poor prognosis and is found in approximately 25% of cases of acute myeloid leukemia (AML)." (PMID 34035227, 2021). "The pronounced sensitivity of the FLT3-ITD/STAT5A signaling axis to DOT1L inhibition raises the possibility that non-MLL-rearranged leukemias with FLT3-ITD mutations, representing 30–40% of acute myeloid leukemias, may also be susceptible to DOT1L inhibition." (PMID 34263728, 2021). "A 60‐year‐old woman previously diagnosed with acute myeloid leukaemia (AML) with fibrosis (normal karyotype, NPM1‐mutated, FLT3‐ITD negative, TET2 mutations (two variants) and SRSF2 mutations detected on our myeloid gene panel) presented with worsening pain and swelling in her right arm and leg." (PMID 35845279, 2021). "Acute myeloid leukemia (AML) is a heterogeneous malignancy with the most common genomic alterations in NPM1, DNMT3A, and FLT3." (PMID 32754299, 2020). "The prognostics implications of patients with acute myeloid leukemia harboring non-canonical FLT3 is unknown." (PMID 32984009, 2020). "Aberrant chromosomal translocation BCR–ABL kinase and activation of FMS-like tyrosine kinase 3 (FLT3) receptor tyrosine can induce STAT 5 activation in CML and Acute myeloid leukemia (AML), respectively." (PMID 30847297, 2019). "STAT5 is activated by FLT3-ITD, which is a constitutively active TK driving the pathogenesis of acute myeloid leukemia (AML)." (PMID 29472718, 2018). "A 56-year-old-male patient was diagnosed in 2009 with an acute myeloid leukemia (AML; French–American–British FAB: M1, cytogentics: FLT3 neg, mDx Hema Vision Multiplex RT-PCR neg., Tryptase pos)." (PMID 26919852, 2016). "In our study, FLT3-ITD and NPM1 mutations were considered in the risk stratification according to NCCN Guidelines (Version 1.2015 Acute Myeloid Leukemia), we included risk stratification but not mutational status of FLT3-ITD and NPM1 as individual variables in our multivariate analysis." (PMID 27528035, 2016). "For example, selective FLT3 (fms-related tyrosine kinase 3) inhibitors, such as AC220 (quizartinib), have been proven clinically effective in acute myeloid leukemia (AML) patients with internal tandem duplications (ITD) in the gene of FLT3." (PMID 25574601, 2015). "The type III receptor tyrosine kinase fms-like tyrosine kinase 3 (FLT3) is expressed on both normal hematopoietic cells and acute myeloid leukemia (AML) cells and regulates their proliferation." (PMID 24040307, 2013). "Indeed, the presence of MLL rearrangements in both acute lymphoblastic leukemia (ALL) and acute myeloid leukemia (AML) seems to relate with high level expression of genes normally expressed in HSCs during the early stages of hematopoiesis, such as FLT3 and HOXA9." (PMID 23977280, 2013).